HMGB1 (high mobility group box 1)
Diseases named in the same sentence as HMGB1 in open-access papers (continued):
Sharing a sentence is not in itself a finding about the gene and the disease.
tumor (continued). "In this study, we constructed a tumor-forming model in nude mice, and revealed that after HMGB1 interference, cell morphology changed, nucleo-plasma specific gravity decreased, wrinkling status appeared, drug-resistant protein expression decreased, and cells showed obvious apoptosis and necrosis." (PMID 37518006, 2023). "There is increasing evidence that tumor-derived substances, including IL-8 and HMGB1, could induce NET formation." (PMID 36050539, 2023). "TIM-3 competes with tumor cell-derived nucleic acids and binds HMGB-1." (PMID 37567938, 2023). "However, recent studies have also shown that early DAMP signals such as HMGB1 can play a role in recruiting tumor infiltrating lymphocytes (TIL), which can be beneficial for additional immunotherapy." (PMID 37210579, 2023). "This could be the direct evidence that HMGB1 induces rapid tumor growth and metastasis, but Lf-GL can refrain HMGB1-mediated tumor progression with high affinity." (PMID 37210579, 2023). "In addition, another study showed that HMGB1 synergistically induced IL-1b release from dc with ATP and that HMGB1-specific antibodies eliminated the ability of dc to contact dying tumor cells to produce IL-1b." (PMID 37305384, 2023). "Extracellular HMGB1 acts as a tumor promoter by accelerating cancer development." (PMID 36982351, 2023). "Furthermore, in the infiltration zone adjacent to the tumor core, we also detected HMGB1, HSP70 and YB1, consistently colocalizing with the adenoviral hexon protein, indicating that ICD was induced exclusively in the XVir-N-31-infected GBM cells." (PMID 37894279, 2023). "Furthermore, in the therapy of ferroptosis+NK cells, tumor cells expressed HMGB1 and PD-L1, and a clear regression of tumor volume after ferumol-mediated ferroptosis and NK cell treatment was observed in a prostate cancer mouse model." (PMID 37213276, 2023). "EVO administration in mice injected with HSC4 cells exhibited suppression of tumor growth, invasion and proliferation indicating that the anti-tumor effects of EVO may be mediated through inhibition of the HMGB1/RAGE signaling pathway." (PMID 37511951, 2023). "This could be interpreted as Lf-GL arrests the tumor-released HMGB1 at an early stage and prevents aggressively worsening tumor growth." (PMID 37210579, 2023). "DAMPs include calreticulin (CRT), Hsp70, ATP, HMGB1, etc., the appearance of which on the surface of dying cells or in the tumor microenvironment help determine whether cell death is immunogenic." (PMID 38131639, 2023). "Secreted HMGB1 acts as an “alarmin” or a “danger signal” that may trigger malignant tumor progression." (PMID 37735586, 2023). "Through the expression of so-called pattern recognition receptors (PRRs), such as Toll-like receptors (TLRs) and RAGE, which recognize DAMPs released from the distressed cells (of which HMGB1 is the prototype), dendritic cells play an essential role in initiating the immune response against tumours." (PMID 36980583, 2023). "In addition to its effects on tumor cell invasiveness, HMGB1 also facilitates tumor progression by interfering with antitumor immunity." (PMID 36831371, 2023). "Typically, the supernatant HMGB1 level was only 1 ng/mL in M-AC group but increased by almost two folds in M-AC + mU@OMVs group, emphasizing the widespread secondary necrosis of apoptotic tumor cells attributed to the highly effective efferocytosis inhibition." (PMID 36966130, 2023). "In addition, increased tumor HMGB1 mRNA and protein expression correlates with the progression of NSCLC patients." (PMID 37759736, 2023). "We found that the Arf1‐ablated tumor cells released HMGB1, oxidized low‐density lipoprotein (oxLDL), and genomic DNA, which might together bind to co‐receptors complex of the CD36/TLR2/TLR6 on the dendritic cell surface." (PMID 37786300, 2023).
tumor (continued). "Combined treatment with the v-raf murine sarcoma viral oncogene homolog B1 inhibitor, and MEK inhibitor may achieve the anti-tumor goal by promoting HMGB1 release and GSDME cleavage in DCs113." (PMID 37705746, 2023). "Therefore, delivery of HMGB1-specific antagonists to the tumor microenvironment can efficiently inhibit tumorigenic, angiogenesis and GBM development." (PMID 37210579, 2023). "Interestingly, 18 days after the INA, some hot spots of the HMGB1 staining were visible, whilst in most of the tumor area, HMGB1 was uniformly distributed (lower two panels)." (PMID 37894279, 2023). "Pyroptosis can induce the increase of CRT and the release of HMGB1 and ATP in tumor cells." (PMID 37316830, 2023). "Nano-DOX (a delivery form of doxorubicin) stimulates the tumor cells and the tumor-associated macrophages (TAMs) to release the cytokine HMGB1, which, through the RAGE/NF-κB pathway, induce PD-L1 in the tumor cells and PD-L1/PD-1 in the tumor-associated macrophages." (PMID 37110415, 2023). "We can conclude that downregulation of this microRNA as a result of stress may suppress the inhibition of high-mobility group protein B1 (HMGB1) and result in tumor proliferation." (PMID 37509697, 2023). "Notably, HMGB1 serves as a double-edged sword in anti-tumor immunity, as an acute increased level of HMGB1 results in the enhancement of ICD." (PMID 37020242, 2023). "ATP release is mediated by active secretion from dying tumor cells preceding the release of HMGB1." (PMID 37243029, 2023). "A proposed model of the pro-tumor or antitumor activities of HMGB1 has been elucidated." (PMID 37626858, 2023). "Generally, intracellular HMGB1 acts as a tumor suppressor and may enhance other tumor suppressors’ activity." (PMID 36982351, 2023). "Suppressing HMGB1 expression down-regulated the molecular level and activity of Bcl-2, blocked the binding of Bcl-2 to autophagy gene Beclin1, and inhibited autophagy, thus promoted the apoptosis of tumor cells." (PMID 37518006, 2023). "Consistent with that expectation, either actively secreted or passively released HMGB1 has been reported to regulate angiogenesis, including promoting endothelial progenitor cells, homing them to tumor tissues, and inducing endothelial cell sprouting and migration." (PMID 37210579, 2023). "HMGB1’s role in tumor development is multifaceted and serves as a double-edged sword." (PMID 38066523, 2023). "However, the translocated HMGB1 from the nucleus governs the tumor cell proliferation, invasion, and metastasis." (PMID 37210579, 2023). "A majority of tumor cells release HMGB1 during externally induced apoptosis and autophagy." (PMID 37098542, 2023). "In addition, the peptide LTX-401 induced the release of ATP and HMGB1, and induced tumour remission with abscopal effect and promoted the establishment of antitumour memory against hepatocellular carcinoma cells in vivo." (PMID 38077402, 2023). "Furthermore, the combination of ERAD inhibitors and moderate dose RT resulted in a remarkable HMGB1 release from dying tumor cells." (PMID 36907982, 2023). "High levels of ROS can enter DCs by diffusion across the plasma membrane or through extracellular vesicles released by tumor cells, affecting the oxidation of high mobility group protein B1 (HMGB1), thereby preventing the maturation of DCs and affecting their antigen-presenting function." (PMID 37876967, 2023). "Our observation that a larger number of correlations was observed between the transcript levels of S100s and HMGB1 in the tumor array than in cells suggests that the tumor microenvironment provides complex transcriptional regulation mechanisms for S100s and HMGB1." (PMID 37627239, 2023). "Inhibition of HMGB1 and NETs significantly delayed tumor proliferation." (PMID 36993957, 2023). "Therefore, in this closed system, all the treatments were found to mitigate tumor-derived HMGB1 secretion, which has a reciprocal effect on angiogenesis." (PMID 37210579, 2023).
tumor (continued). "AGEs incite RAGE along with HMGB1 promoting oxidative stress and tumour pertinent inflammation." (PMID 37970208, 2023). "In addition to CEACAM-1, three other ligands are expressed on tumor cells, galectin-9, high mobility group box 1 (HMGB1), and phosphatidylserine (PtdSer)." (PMID 37055849, 2023). "Besides tumor-derived cytokines and immune complexes, several PAMPs and DAMPs, such as LPS and HMGB1, are considered potent inducers of NOX-independent NETosis." (PMID 36050539, 2023). "Moreover, it is known that tumor cells secrete HMGB1 to recruit endothelial cells and facilitate a tumor vascular system by the crosstalk." (PMID 37210579, 2023). "This suggests that the tumor environment influences the expression of S100 proteins and HMGB1." (PMID 37627239, 2023). "For example, beside extensively engaging in tumor development and progression, HMGB1 indeed had profound effects in remodeling TME, and its inhibition could enhance ICI efficacy." (PMID 36671569, 2023). "We showed the dynamics of immune checkpoint pairs under a tumor HMGB1 environment." (PMID 36993954, 2023). "Remarkably, there was insignificant correlation between intracellular HMGB1 expression and tumor-infiltrating immune cells; the correlation coefficient between genes involved in regulating the synthesis of ATP and tumor-infiltrating immune cells was also not significant." (PMID 36907982, 2023). "In addition, ferroptosis produces lipids, and their interactions can influence the release of HMGB1, which controls tumor immunity." (PMID 37973895, 2023). "Cell surface TLRs, including TLR1, TLR2, TLR4, TLR5, TLR6, and TLR10, can actively capture extracellular information, including tumor cell-released DAMPs or apoptotic cancer cell fragments, such as HMGB1, HSP, and S100, as well as extracellular vesicles containing changed cell components." (PMID 36911674, 2023). "Within the ablation zone, early high mobility group box protein 1 (HMGB1) release and necroptosis were accompanied by immunogenic cell death transcriptional responses in tumor cells and innate immune activation transcriptional responses in infiltrating myeloid and natural killer (NK) cells." (PMID 36756111, 2023). "While HMGB1 expression is not directly associated with survival, strong epithelial cytoplasmic HMGB1 is associated with an ‘immune cold’ tumour microenvironment which is associated with poor survival outcomes." (PMID 36980751, 2023). "HMGB1 seems to have both tumor‐promoting and tumor‐suppressive properties in malignancies." (PMID 37752941, 2023). "Moreover, tumor cell-induced cytokines such as HMGB1 triggered macrophage apoptosis while encouraged tumor cell growth." (PMID 37090721, 2023). "The switch to reduced nuclear HMGB1 expression was between normal and T1 tumour stage (p < 0.001)." (PMID 36980751, 2023). "Consequently, Lf-GL has the potential to mitigate immunosuppression resulting from HMGB1 downregulation in the tumor microenvironment." (PMID 37210579, 2023). "The release of HMGB1 from the apoptotic tumor cells (AC group) was obvious but faint in M-LC group." (PMID 36966130, 2023). "The upregulation of HMGB1 is a critical molecular event of DAMP (danger-associated molecular pattern) signalling, implying the activation of the proinflammatory response induced by tumour necrotic debris after IRE ablation." (PMID 37433774, 2023). "Cathepsins B and L are useful biomarkers for the efficacy of reovirus-mediated tumor cell killing, and serum high-mobility group box 1 (HMGB1) protein was reported to be a potential predictive and prognostic biomarker for adenoviruses combined with immunotherapy." (PMID 38169820, 2023). "Recently, we demonstrated that hyperthermic-mediated secondary apoptosis of tumor cells induces the release of HMGB1, which, in turn, supports the activation of dendritic cells and sustains the activation of a tumor-specific adaptive immune response that restricts prostate cancer outgrowth." (PMID 36911674, 2023).
tumor (continued). "HMGB1 is a tumor-promoting DAMP in the tumor microenvironment." (PMID 37210579, 2023). "After that, we looked at whether the high mobility group box 1 protein (HMGB1) secreted by tumor cells that were dying after PTT could act as a catalyst for inflammation, draw in different immune cells, and induce DC maturation." (PMID 36593797, 2023). "Camphene may induce ICD in apoptotic tumor cells by inducing ER stress and increasing HMGB1 and CRT expression." (PMID 37705051, 2023). "It is known that HMGB1 function is related to the redox status of three cysteines (C23, C45, C106) and that the disulfide-semi-oxidized state works as a cytokine promoting inflammation and tumor progression." (PMID 36769076, 2023). "HMGB1 is related to the immunogenicity of tumour cell ferroptosis." (PMID 36600313, 2023). "In cervical cancer, tumor derived HMGB1 dampens the IFN-secreting ability of pDCs." (PMID 37817484, 2023). "Additionally, HMGB1 can bind to receptors on immune cells, promoting tumor growth and immune evasion." (PMID 37520371, 2023). "For example, anthracyclines and oncolytic viruses induce immunogenic cell death (ICD) in which dying tumor cells release or express danger-associated molecular patterns (DAMPs) such as calreticulin (CRT), High Mobility Group Box-1 (HMGB-1), and heat shock proteins (HSP-70 and HSP-90)." (PMID 37370701, 2023). "Tumor cells also release damage-associated molecular patterns (DAMPs) after IR, including high-mobility group box 1 (HMGB1), heat shock proteins (HSPs), and calreticulin (CRT), which mediate phagocytosis of antigen-presenting cells (APCs) and initiate tumor-specific T cell activation." (PMID 37600785, 2023). "Among the HDP, some have been reported as ICD inducers, such as LTX-315 which, in addition to its effect in reducing pro-tumour immune cells, has also been reported to induce the emission of DAMPs (calreticulin, HMGB1 and ATP) and to induce in vivo myeloid and T lymphocyte tumour infiltration." (PMID 38077402, 2023). "However, when looking at the data from the tumor array, we observed 33 statistically significant correlations between S100s and S100/HMGB1." (PMID 37627239, 2023). "On the other hand, HMGB1 produced by the tumor-specific macrophages can regulate the microenvironment through IL-6/STAT3/(programmed death-ligand 1) PD-L1 pathway and IL-6/NF-κB/(matrix metalloproteinase 9) MMP-9 pathway leading to further immunosuppression and aggressive phenotypes of OSCC cells." (PMID 37511951, 2023). "A positive correlation was also found between HMGB1 levels and tumour size." (PMID 37298365, 2023). "Given their published data, it is reasonable to hypothesize that tumor-derived HMGB1 induced by RT elicits endogenous TLR2 signaling and initiate a CD8+ T cell-dependent immune response." (PMID 37112730, 2023). "HMGB-A box, a competitive antagonist of HMGB1, and glycyrrhizin, a small molecule inhibitor as well as RAGE antagonist peptide and ethyl pyruvate have been shown to block extracellular HMGB1 and affect cell proliferation and invasion in vitro, as well as leading to tumor growth suppression in vivo." (PMID 37511951, 2023). "Notably, ORFV-induced cell death correlated with the release of immune stimulant High Mobility Group Box 1 (HMGB1) into the tumor cell supernatant, further supporting that ORFV-triggered pyroptotic cell death is pro-inflammatory." (PMID 36641456, 2023). "The co-incubation of M2 macrophages with apoptotic tumor cells (M-AC group) significantly decreased the HMGB1 level owing to the efferocytosis effect of M2 macrophages, and the addition of OMVs did not ameliorate the HMGB1 liberation due to the feeble efferocytosis inhibition ability of OMVs alone." (PMID 36966130, 2023). "Administration of exogenous HMGB1 to tumor-bearing mice increased tumor growth." (PMID 36831371, 2023).
tumor (continued). "Activation of the HMGB1-RAGE signaling axis activates MAPK pathways, inducing Nuclear Factor-κB (NF-κB) activity that is ultimately linked to inflammatory response and cancer cell proliferation, as well as tumor invasiveness." (PMID 37511951, 2023). "Furthermore, cleavage of GSDME and release of HMGB1 activate DCs, eventually leading to T cell proliferation, thereby exerting anti-tumor effects." (PMID 37705746, 2023). "In addition to its role in the nucleus, HMGB1 functions in the cytoplasm as an extracellular signaling protein during inflammation, cell differentiation, tumour progression, cisplatin resistance and induces the hall marks of ICD." (PMID 37537587, 2023). "However, intracellular HMGB1 also has effects on tumor progression by mediating DNA repair mechanisms and NF-κB signaling." (PMID 37759736, 2023). "Additionally, the interaction of HMGB1, which is found between tumor-infiltrating dendritic cells and TIM-3, inhibits the activity of innate immune response within the tumor microenvironment." (PMID 37444609, 2023). "Preventing HMGB1-mediated tumor growth and metastasis should be further studied." (PMID 37168380, 2023). "Following radiation therapy, the release of S100B and HMGB1 from injured brain parenchyma or tumor cells may activate downstream RAGE-mediated inflammatory pathways as occurs in stroke and trauma." (PMID 36652782, 2023). "The anti-tumor activity of Cisplatin could be boosted by increasing the nuclear accumulation of HMGB1 protein, an inhibitor of Cisplatin DNA-adduct repair." (PMID 38001683, 2023). "Currently, a Phase 1 multicenter clinical trial is in progress, evaluating the pharmacodynamics, safety, and anti-tumor activity of the orally available small molecule HMGB1 inhibitor SB17170, in patients with metastatic solid tumors who have failed previous treatment (SB17170 clinicaltrials.gov)." (PMID 37511951, 2023). "Therefore, Lf-GL effectively inhibited the cascade (tumor angiogenesis, tumor progression, infiltration into surrounding tissues, etc.)induced by HMGB1 secreted from necrotic tumor." (PMID 37210579, 2023). "Our data cumulatively suggest that increased HMGB1 expression in CRC orchestrates a pro-tumour microenvironment, and HMGB1 may therefore be a therapeutic target of interest to improve endogenous anti-tumour immunity and chemosensitivity." (PMID 36980751, 2023). "Tumour cells that produce ferroptosis acetylate HMGB1 and release HMGB1 through autophagy." (PMID 36600313, 2023). "HMGB1 does not directly impact survival but is associated with an ‘immune cold’ tumour microenvironment which is associated with poor survival (p < 0.001)." (PMID 36980751, 2023). "HMGB1 is the gene encoding the non-histone protein HMGB1, which increases transcription and acts as an extracellular signaling molecule during tumor progression." (PMID 37240338, 2023). "Moreover, a positive correlation of HMGB1 levels with tumor volumes, C‐reactive protein (CRP) levels, infections, and grade three toxicity (RTOG) was observed." (PMID 34671818, 2022). "The striking observation that soluble HMGB1 derived from tumor cells mediates the production of proliferating VEGF+ B cells, prompted us to ask if suppressing HMGB1 could interfere with this proangiogenic phenotype." (PMID 34617194, 2022). "However, the biology of intracellular HMGB1 in the tumor (as detected by immunohistochemistry in the tumor tissue) is different from the role of extracellular HMGB1, which mainly serves as a danger signal for the immune system." (PMID 34671818, 2022). "More studies are needed to understand the complex role of HMGB1 during tumor development." (PMID 36032129, 2022). "Herein, we investigated whether high mobility group box 1 (HMGB1) is a potential biomarker of BNCT response in tumor cells and mice in combination with 10B-p-boronophenylalanine in the Kyoto University Nuclear Reactor." (PMID 35336794, 2022).